MSLN (mesothelin)
Diseases named in the same sentence as MSLN in open-access papers (continued):
Sharing a sentence is not in itself a finding about the gene and the disease.
cancer (continued). "The associated phase 1/2a trial (NCT03872206) is a multicenter, open-label study designed to evaluate the safety, tolerability, PK and activity of HPN536 in up to 80 patients with advanced cancers associated with MSLN expression." (PMID 31463062, 2019). "In the promoter region of another MM marker gene MSLN encoding mesothelin, a “cancer-specific” element driving mesothelin overexpression in cancers was discovered." (PMID 30555628, 2018). "Although MSLN is implicated in many cancers, the role of MSLN is still poorly understood warranting further investigation and clinical trial studies." (PMID 30134520, 2018). "As trace amount of MSLN can be detected in the blood of some patients with MSLN-positive cancers, in vitro diagnostic tests have been developed not only for diagnosis but also for following the course of some of these patients." (PMID 25883990, 2015). "The results on MPM cells were in agreement with the findings observed in PC and OC cells, suggesting that all the MSLN-expressing cancer cells show a significant loss of viability upon MSLN depletion." (PMID 24465798, 2014). "Mesothelin is a cell surface associated antigen expressed on mesothelial cells and in some malignant neoplasms." (PMID 25506917, 2014). "A panel of KOC, S100P and mesothelin with at least 2 biomarkers positive achieved almost perfect diagnostic accuracy in the differentiation of carcinoma from normal tissue." (PMID 25071419, 2014). "In the univariate analysis, MUC1 and MSLN expression were associated with aggressive cancer biology (i.e. short survival group) and MUC2 expression was associated with favorable biology (i.e. long survival group)." (PMID 22792233, 2012). "The current study is a significant step forward in understanding the role of MSLN in PC pathogenesis, especially with regards to cancer cell survival in a highly inflammatory milieu, a hallmark of this deadly cancer." (PMID 21880146, 2011). "Finally, given that MSLN has been linked to both the development and metastasis of cancer, it is a viable target for cancer treatment." (PMID 40227616, 2025). "Aside from its cancer-associated expression, MSLN is differentially expressed in multiple tissues." (PMID 41335396, 2025). "Furthermore, targeting MSLN prevents its interaction with cancer antigen CA-125, which has been implicated in supporting metastases." (PMID 40402266, 2025). "This second cluster could represent a cancer-associated fibroblast (CAF) population characterized by low expression of MSLN and WT1 and high expression of ACTA2, S100A4, COL5A2, SPARC, and FN1." (PMID 36901697, 2023). "Some authors have linked the OE of MSLN to increased expression of CSCs, which could thus contribute to explaining the association of MSLN with cell aggressiveness and cancer progression." (PMID 35162954, 2022). "Immunohistochemical studies confirmed the limited expression of MSLN in healthy tissues (mesothelial cells of the pleura, pericardium, peritoneum, fallopian tubes, and tonsils), underlining the potential to exploit it as target for cancer therapy." (PMID 33418877, 2021). "Only mesothelin expression was associated with worse prognosis in several carcinomas." (PMID 33832498, 2021). "However, the overexpression of MSLN has been associated with cancer cell proliferation, increased local invasion and metastasis, and resistance to apoptosis induced by cytotoxic agents." (PMID 30031396, 2018). "Human and mouse mesothelin expression have been implicated in the development of cancer." (PMID 26931187, 2016). "CA125, a membrane associated ovarian cancer antigen, has been reported to interact with MSLN, and it has been suggested that this interaction may facilitate ovarian cancer metastasis." (PMID 25118887, 2014). "Also, mesothelin upregulation in carcinomas has been associated with a misregulation of Wnt signal transduction pathway." (PMID 25477701, 2014).
cancer (continued). "Furthermore, TEAD1 directly regulates the transcription of Mesothelin (MSLN) that is highly expressed in several cancers and is a good candidate for a diagnostic marker." (PMID 23029054, 2012). "However, like MUC1, there was a strong association between MSLN expression and early cancer-specific mortality (p<0.0001)." (PMID 22792233, 2012). "Furthermore, Mesothelin silencing caused a significant increase in fraction of cancer cells in S-phase." (PMID 22485139, 2012). "Additionally, MSLN has been associated with specific features of the peritoneal basal membrane, including decreased collagen density and increased fenestrations, thereby enhancing tissue permeability to cancer cells." (PMID 41335396, 2025). "All eight nucleotides in the MCAT element were shown to be essential for its function; conversely, the SP1-like element was shown to have two mutations suggesting, that the cancer-specific expression of MSLN is thought to occur through the binding of an unknown transcription factor." (PMID 30134520, 2018). "This review provides an up-to-date comprehensive overview regarding the role of mesothelin in cancer." (PMID 41994562, 2026). "The very low intensity of staining in some blue MSLN+ cancer cells is attributable to the heterogeneity of hMSLN expression within this cell line." (PMID 41477550, 2025). "A phase I dose-escalation study of SS1P enrolled 34 individuals with mesothelin-positive cancers, defined as ≥30% cells with mesothelin expression on IHC staining." (PMID 41375064, 2025). "Immunotherapies targeting mesothelin have the potential to completely transform the way cancer is therapy in patients with limited options." (PMID 40227616, 2025). "Although early, CAR-T has shown some promising early results in solid tumors targeting mesothelin which is a molecule that is broadly expressed in many cancers such as various cancers such as lung, pancreas, breast, ovarian, and others." (PMID 41018125, 2025). "In this study, the authors observed a positive correlation between serum MSLN levels and cancer stage, as well as postoperative decrease in MSLN concentrations." (PMID 41335396, 2025). "Mesothelin physiologic expression is restricted to mesothelial cells, but is overexpressed in various cancers with poor prognosis that yet lack targeted therapies." (PMID 40293556, 2025). "By integrating molecular insights with translational perspectives, this work provides a comprehensive overview of MSLN biology and its emerging therapeutic relevance in cancer." (PMID 41335396, 2025). "This selective overexpression in tumors, along with its restricted distribution in normal tissues, makes MSLN both a potential biomarker for cancer detection and prognosis and a promising target for the development of MSLN-directed therapies." (PMID 41335396, 2025). "Mesothelin is a glycoprotein overexpressed in various cancers, with limited expression in healthy tissues." (PMID 40833585, 2025). "Among the targets of cancer recently identified, the glycoprotein mesothelin has been proposed as a relevant target for tumor diagnosis and therapy." (PMID 40833585, 2025). "In contrast to the extensive body of research on MSLN as a diagnostic biomarker for PM, only a limited number of studies have investigated its role in other MSLN-expressing cancers." (PMID 41335396, 2025). "In this work, we describe the first Affitins capable of binding to hMSLN and demonstrate their potential usefulness for future applications in targeted therapy of MSLN-expressing cancers." (PMID 41477550, 2025). "After establishing the role of MSLN as a potential cancer antigen with the K1 antibody, the first MSLN-targeted cancer therapies employed proteins or Abs conjugated with cytotoxic molecules." (PMID 41335396, 2025). "Consistently, forced CD24 overexpression was able to rescue the aggressive cancer phenotype in the MSLN-silenced cells, reestablishing the immune-suppressive TME and promoting immune evasion." (PMID 41335396, 2025).
cancer (continued). "This study aims to determine how MSLN prevents cancer cells from entering a state called senescence, where they stop growing." (PMID 40563707, 2025). "This ADC utilizes a humanized anti-mesothelin antibody linked to a cytotoxic agent, enabling selective targeting and killing of mesothelin-positive cancer cells." (PMID 41347223, 2025). "Mesothelin is overexpressed in many cancers and interacts with carbohydrate antigen‐125 (CA‐125, also known as mucin‐16 or MUC16)." (PMID 40923371, 2025). "Given its overexpression in numerous solid tumors and its involvement in cancer progression, MSLN represents an attractive therapeutic target." (PMID 41335396, 2025). "Mesothelin (MSLN) is a glycosylphosphatidylinositol-anchored cell surface protein involved in various aspects of cancer biology, including promoting cell adhesion, proliferation, and survival." (PMID 40236691, 2025). "Mesothelin, a glycosylphosphatidylinositol (GPI)-linked protein, is usually expressed on mesothelial cells but is overexpressed in many cancers, promoting tumor growth, survival, and metastasis." (PMID 40281554, 2025). "Given CD47’s role in immune evasion, a MSLN-targeting approach was developed to block CD47-dependent escape mechanisms in cancer cells." (PMID 41335396, 2025). "Since MSLN has been shown to play an active role in cancer progression, particularly in metastatic dissemination and in promoting the establishment of an immunosuppressive TME, its prognostic value has also been investigated." (PMID 41335396, 2025). "The first in-human Phase I clinical trial of Anetumab ravtansine (AR) started in 2011 and revealed that AR was well-tolerated in MSLN-positive cancer patients (NCT01439152)." (PMID 41335396, 2025). "The homodimerization of the best candidate, resulting in a dimer of 15 kDa, enabled its binding to cellular MSLN on the surface of PM cancer cells, with an affinity of approximately 2 nM." (PMID 41477550, 2025). "Despite its immense potential in cancer progression, the complicated regulatory and physiological functions of MSLN remain unexplored." (PMID 40227616, 2025). "A similar pattern of behavior has been observed in PDAC, where knocking out MSLN prevents the formation of heterotypic aggregates and the peritoneal dissemination of cancer cells." (PMID 41335396, 2025). "The FDA orphan drug designation for BZD1901, a CAR-T cell therapy targeting MSLN, further demonstrates the promise of MSLN-targeted therapies in cancer treatment." (PMID 41436559, 2025). "Chimeric antibodies like MORAb-009, recombinant immunotoxins like SS1P and new medicines like HN1 and m912 have all demonstrated encouraging outcomes in recent times for MSLN-targeted cancer therapy." (PMID 40227616, 2025). "The overexpression of MSLN across multiple cancer types has prompted studies aimed at evaluating its role in cancer development and progression." (PMID 41335396, 2025). "Although the identification of a unified model describing the involvement of MSLN in cancer onset and progression remains challenging, additional evidence continues to emerge, gradually clarifying its biological significance." (PMID 41335396, 2025). "Taken together, these data highlight the multiple roles of MSLN in cancer biology and its promise as a therapeutic target." (PMID 41335396, 2025). "MSLN is a glycoprotein present in the cell membrane of mesothelial cells and is overexpressed in specific cancers, such as OC." (PMID 41462867, 2025). "The complex control, cellular functions and clinical significance of MSLN in the advancement of cancer are highlighted in this review." (PMID 40227616, 2025). "In cancer, MSLN is overexpressed not only CRC but also in mesothelioma, ovarian cancer, pancreatic cancer, as well as in cervical, endometrial, biliary cancers, uterine serous carcinoma, cholangiocarcinoma, and pediatric acute myeloid leukemia." (PMID 40236691, 2025).
cancer (continued). "MSLN networks with a cancer antigen CA125/MUC16 trigger a chain of signaling events, which in turn suppresses a Dickkopf-1 (DKK1), a secreted protein that inhibits the Wnt signaling pathway and stimulates cell migration." (PMID 40227616, 2025). "In recent years, a growing body of evidence has contributed to shedding light on the mechanisms through which MSLN promotes cancer progression." (PMID 41335396, 2025). "Although not directly transferable to malignancy, these observations, along with the well-established link between fibrosis and cancer, strongly support further research into the role of MSLN in this context." (PMID 41335396, 2025). "A phase I/IIa study of HPN536 in patients with mesothelin-expressing cancers, including PM, was recently completed, and the publication of these results is pending (NCT03872206)." (PMID 41375064, 2025). "Currently, a large number of experiments have been performed in mouse models, and a set number of clinical trials have been performed to verify the therapeutic effect of MSLN CAR-T-cell therapy in different types of cancer with high MSLN expression." (PMID 39023820, 2024). "CAR-T therapy has demonstrated lasting clinical responses in various cancers, with tumors expressing higher levels of mesothelin in advanced stages (III and IV) and in high-grade EOC." (PMID 39206199, 2024). "MSLN expression was observed in the cytoplasm and the membrane of cancer cells, whereas NCL expression was identified in the cytoplasm and nucleus." (PMID 39294656, 2024). "From the data, we observed that both MSLN & CEA antigens have enrichment terms with respect to the extracellular-related functions and are implicated in several cancers including PDAC and CRC in which the KRAS is highly mutated." (PMID 39453574, 2024). "Combination of anti-Mesothelin CAR-NK-92 cells with chemotherapy revealed increased elimination of cancer cells as compared to monotherapy settings." (PMID 39781381, 2024). "The overexpression of MSLN in a variety of malignant tumors makes it an ideal target for immunotherapy in solid tumors." (PMID 39023820, 2024). "A recent study used MSLN to target various solid cancers, including CRC, and found that MSLN CAR-T cells killed not only MSLN-positive cancer cells in vitro but also MSLN-positive CDX and PDX solid tumors in vivo." (PMID 38533510, 2024). "Mesothelin is a well-known marker of solid tumors that promotes cancer cell proliferation and survival." (PMID 38396817, 2024). "When cocultured with MSLN-positive cancer cells, CAR-T cells overexpressing shRNA targeting cell-intrinsic A2aR produced a large number of cytokines and exhibited significantly increased cytotoxicity in vitro." (PMID 39023820, 2024). "Further exploratory analyses revealed that CTLA4, PDCD1, and the cancer antigens MSLN, MUC1, EPCAM, and PROM1 presented significantly increase expression levels in the high-risk subtype group." (PMID 39712016, 2024). "The cell surface glycoprotein antigen Mesothelin (MSLN), which is a 40 kDa in size associated with cellular differentiation, is frequently highly expressed in some malignant tumors." (PMID 38628720, 2024). "In a phase I trial on advanced mesothelin-expressing (MSLN+) cancers, including MM, amatuximab in monotherapy demonstrated a good safety profile." (PMID 38893092, 2024). "The collective results clearly indicate that mesothelin alters cancer metabolism to facilitate a rapid production of ATP." (PMID 38396817, 2024). "Mesothelin-targeted TCR-T cells have shown manageable toxicity profiles and high rates of disease control in advanced mesothelin-expressing cancer patients (NCT03907852)." (PMID 38785789, 2024). "Anti-mesothelin CAR T cells (mesoCAR T cells) are under clinical trials for several cancer types, including EOC." (PMID 39206199, 2024). "Various phase I/II studies are testing new therapies for the most promising targets, including CAR T and cancer vaccines versus MSLN, PRMT5-MTA, PI3K, andYAP/TEAD inhibitors and PARPi." (PMID 38893092, 2024).
cancer (continued). "One of the attractive cancer antigens for the treatment of solid tumours is mesothelin (MSLN), a cell surface glycoprotein that is highly expressed in many solid tumours but has limited expression on normal human tissues." (PMID 39548594, 2024). "The T-cell signalling related responses of all the domains of the designed CAR protein and cancer antigens (MSLN & CEA) were predicted by the protein–protein interaction (PPI) network using the STRING and Cytoscape." (PMID 39453574, 2024). "Mesothelin is a promising target antigen as it is aberrantly expressed on cancer cells and has only limited expression in healthy adult tissues." (PMID 39781381, 2024). "MSLN, a membrane-bound protein, is sparingly expressed in normal cells but is markedly overexpressed in various cancer cells, including TNBC." (PMID 39294656, 2024). "MSLN is a promising target for anti‐cancer personalised therapy with anticipated low toxicity due to its limited expression in healthy or essential tissues." (PMID 37040900, 2023). "Ever since its discovery, mesothelin has been an interesting target antigen in investigations relating to cancer immunotherapy." (PMID 38146364, 2023). "The low expression of mesothelin on healthy tissues and its overexpression in malignancy, particularly carcinoma, has made it an promising target for antibody-based cancer treatments." (PMID 37880707, 2023). "Because MSLN is highly expressed on the surface of many cancers, it is now considered an excellent target for antibody-based immunotherapies." (PMID 36968141, 2023). "Due to its differential expression between cancer and normal tissues and its role in tumorigenesis, MSLN can be considered a potential target." (PMID 37359558, 2023). "Promising clinical results from targeting MSLN in patients with cancer have stimulated searches for more effective mAbs, which can benefit from our structural studies of MSLN." (PMID 36968141, 2023). "Due to its differential expression between cancer and normal tissues and its role in tumorigenesis, MSLN can be considered as a potential target for cancer immunotherapy." (PMID 37359558, 2023). "Ultimately, however, Cxcr3 was critical for mitigating cancer cell dissemination following immunotherapy with CD40 agonist + anti-PD-L1 or T cell receptor engineered T cell therapy targeting mesothelin." (PMID 36472588, 2023). "MSLN is a glycoprotein and is also elevated in many types of cancer, including ovarian, lung, and PDAC." (PMID 37894284, 2023). "Several studies have reported the use of anti-MSLN mAbs conjugated to infrared/near-infrared fluorochromes in different cancer pathologies." (PMID 37388728, 2023). "The capacity of nanobody S1 to target MSLN+ cells was evaluated by flow cytometry on a panel of cancer cell lines from different cancers, expressing various levels of MSLN and of its ligand MUC16." (PMID 37388728, 2023). "Since MSLN is a highly specific antigen in several cancers, CAR-T therapy has been considered to be a promising strategy for the treatment of these cancers." (PMID 37359558, 2023). "In fact, previous studies have indicated that CA125 on the surface of cancer cells interacts with the mesothelin molecule on the surface of mesothelial cells, promoting cell adhesion to mesothelial cells and facilitating the formation of peritoneal metastasis." (PMID 37833730, 2023). "Mesothelin (MSLN) is overexpressed in a wide variety of cancers with few therapeutic options and has recently emerged as an attractive target for cancer therapy, with a large number of approaches currently under preclinical and clinical investigation." (PMID 37388728, 2023). "MSLN promotes cancer cell invasion and migration by increasing MMP-7 expression, leading to ECM degradation mediated by the MAPK/ERK and JNK signaling pathways." (PMID 37835395, 2023). "The growth of cancer cells in the peritoneal cavity of MSLN knockout mice was greatly reduced compared to wild-type mice." (PMID 35326701, 2022).